GCG (glucagon)
Diseases named in the same sentence as GCG in open-access papers (continued):
Sharing a sentence is not in itself a finding about the gene and the disease.
Hypoglycemia (continued). "HI is diagnosed by demonstration of increased insulin secretion and actions during hypoglycemia, including detectable insulin, low free fatty acids (FFAs) and beta-hydroxybutyrate (BOHB), and a glycemic response to glucagon administration during hypoglycemia." (PMID 39483531, 2024). "Neonates have limited counterregulatory mechanisms against hypoglycemia, responding by reducing insulin secretion and increasing glucagon, epinephrine, growth hormone, and cortisol to mobilize glucose and fatty acids." (PMID 39006567, 2024). "During hypoglycemia, the glucagon concentrations were lower in the patients with CP and type 2 diabetes (p < 0.05)." (PMID 39596226, 2024). "Glucagon and insulin play an important role in hypoglycemia counterregulation and in restoring normal glucose homeostasis." (PMID 38397994, 2024). "α cells are responsible for secreting the hormone glucagon, which is essential for the regulation and control of hypoglycemia in the body’s metabolic system, and zinc plays a crucial role as a signal molecule in glucagon secretion." (PMID 38169461, 2024). "While dysregulated glucagon secretion by alpha cells plays a role in these conditions, it is also important to note that hypoglycemia in T1D occurs commonly after insulin administration." (PMID 39594662, 2024). "Secretion of glucagon, which forms the first line of defence against hypoglycaemia, is controlled by multiple pancreatic-alpha-cell autonomous and non-autonomous mechanisms." (PMID 38017352, 2024). "The application of glucagon microdosing with multiple daily injections has recently been reported for treatment of spontaneous hypoglycemia following TPIAT." (PMID 39450137, 2024). "Recently, the first generic glucagon for injection was approved for the treatment of severe hypoglycemia." (PMID 38771849, 2024). "Sleep-related changes in hormonal secretion, such as reduced release of counterregulatory hormones (e.g., glucagon, epinephrine, growth hormone), contribute to impaired hypoglycemia awareness during sleep." (PMID 38397994, 2024). "While glucagon’s release is stimulated by hypoglycemia, starvation, exercise, and protein-rich meals, insulin release is stimulated by a hyperglycemic condition." (PMID 38921471, 2024). "Two new glucagon analogues for treating hypoglycemia with 4 weeks of durability at room temperature are approved by FDA." (PMID 37715091, 2024). "The study investigated aspects such as insulin administration, hypoglycemia management, and the use of glucagon." (PMID 39195172, 2024). "Mini-dose glucagon is a safe and effective intervention for the prevention and treatment of mild to moderate hypoglycemia in individuals with T1D." (PMID 39944479, 2024). "Using clamp techniques, our research group has demonstrated that individuals with overweight and insulin resistance have an accentuated HPA axis response to hypoglycemia and an impaired reduction of glucagon during hyperglycemia." (PMID 37708362, 2024). "Control signal of the proposed controller is smooth, not aggressive and always non-negative, it doesn't need any excessive method or algorithm to inject glucagon or glucose to avoid hypoglycemia." (PMID 38186949, 2024). "Dasiglucagon is a novel glucagon analogue under development for the prevention and treatment of hypoglycemia in patients with CHI." (PMID 37930757, 2024). "As such, the combined effects of low glucose and adrenaline can produce a robust glucagon response, facilitating rapid recovery from hypoglycaemia." (PMID 38646167, 2024). "Strikingly, insulin-induced hypoglycemia resulted in significantly smaller elevations of plasma glucagon levels in α-GsKO mice, probably partially due to the reduction in pancreatic glucagon content caused by α-cell Gαs deficiency." (PMID 38879678, 2024).
Hypoglycemia (continued). "She developed symptomatic hypoglycemia after 3 h, bloodwork was drawn, and she received 1 mg of intravenous glucagon with an increase in serum glucose 10 min later to 4.3 mmol/L and resolution of hypoglycemia symptoms." (PMID 38432069, 2024). "It is characterized by a combination of compromised physiological defenses against hypoglycemia, i.e., a decrease in glucose lowering insulin, and an increase in the glucose raising hormones glucagon and adrenaline." (PMID 39375537, 2024). "This is supported by the observations that impaired counterregulatory glucagon secretion in response to hypoglycemia still occurs in humans with spinal cord transections and in the denervated transplanted human pancreas." (PMID 38612880, 2024). "Outcomes show that in the female rat, VMN SF-1 does not affect circulating glucose profiles in V- or INS-injected animals or corticosterone or glucagon secretory responses to hypoglycemia." (PMID 39401164, 2024). "The glucagon administration icon will be displayed when the avatar experiences hypoglycemia, indicating the appropriate action to take." (PMID 38713496, 2024). "Patients with more severe T1D require more time for glucose levels to normalize after insulin-induced hypoglycemia and experience prolonged low plasma glucagon levels, highlighting the role of glucagon in managing hypoglycemia." (PMID 39594662, 2024). "Studies show that micro-boluses of glucagon correct hypoglycemia when insulin levels are low but often fail to influence on glucose levels when insulin levels are high." (PMID 37715091, 2024). "In type 1 diabetes (T1D), impaired glucagon release in response to low blood glucose levels (e.g., after an insulin injection) can lead to severe hypoglycemia and even death." (PMID 38879678, 2024). "Experimental studies have provided evidence that type 1 diabetes mellitus suppresses the stimulatory effect of vasopressin on the release of glucagon during hypoglycemia." (PMID 39769071, 2024). "To explore the potential involvement of α-cell Gs signaling in hypoglycemia-induced glucagon secretion, we treated control and α-GsKO mice with exogenous insulin (1 U/kg, i.p.)." (PMID 38879678, 2024). "Conversely, fasting glucose and HbA1c were the strongest predictors of low GH levels during hypoglycemia and elevated, i.e. less suppressed glucagon levels during hyperglycemia, respectively." (PMID 37708362, 2024). "Ca2+ release from the ER plays a key role in glucagon secretion and α-cell [Ca2+]i activity stimulated by hypoglycaemia." (PMID 38646167, 2024). "During hypoglycemia, the glucagon response is impaired in patients with type 1 diabetes, whereas glucagon is inappropriately secreted after a meal." (PMID 38446636, 2024). "In our previous study, a single bout of HIIT resulted in greater adrenaline, noradrenaline, glucagon and total and autonomic symptom scores during next-day hypoglycaemia, although only the adrenaline and total symptom responses were statistically significant." (PMID 38010533, 2024). "Taken together, these points illustrate that while glucagon is necessary to prevent hypoglycemia, it also has diabetogenic effects." (PMID 39594662, 2024). "Pancreatic perfusion with insulin secretagogues was shown to prevent the release of glucagon in response to hypoglycemia in humans." (PMID 38612880, 2024). "Story and Wilson found that dasiglucagon is more effective than glucagon in the management of hypoglycaemia in terms of efficacy and stability." (PMID 38977507, 2024). "In 1922, Kimball and Murlin identified glucagon as a potent antihypoglycemic factor released by the pancreas, responsible for increasing blood glucose levels in the face of hypoglycemia." (PMID 38477666, 2024). "Our findings finally provide an experimental rationale for the use of agents that reduce somatostatin action or secretion as a means of restoring hypoglycaemia-induced glucagon secretion in T1D." (PMID 39313541, 2024).
Hypoglycemia (continued). "Aside from being used as a drug to reduce hypoglycemia, glucagon is also used to reduce intestinal motility in clinical investigations and examinations." (PMID 37715091, 2024). "Mini-dose glucagon successfully treated the induced mild hypoglycemia following ethanol intake (glucose increased by 2.0 mmol/L [36 mg/dL]), but the effect was somewhat attenuated compared to that seen in the placebo (no ethanol) group." (PMID 39944479, 2024). "In T2D vs ND, glucagon levels were higher and less suppressed during the hyperglycemic clamp whereas growth hormone (GH) levels were lower during hypoglycemia (P < .05)." (PMID 37708362, 2024). "T2D rats also had lower c-peptide levels at baseline and a blunted glucagon counterregulatory response to hypoglycemia when subjected to the ITT." (PMID 38510652, 2024). "Glucagon secretion is stimulated during hypoglycemia and is suppressed during hyperglycemia, providing the first line of defense in glucose counter-regulation." (PMID 38414818, 2024). "Cancer cells have more demand for glucose than normal cells, which can lead to hypoglycemia and stimulate the increase of glucagon." (PMID 39687883, 2024). "Patients experience both aberrantly elevated glucagon levels (hyperglucagonemia), further exacerbating their hyperglycemia, and impaired alpha cell response to iatrogenic hypoglycemia secondary to insulin therapy." (PMID 39594662, 2024). "Even so, we hold that focus should turn to the potential of enhancing the absorption of insulin from the SC tissue by utilizing the vasodilative properties of glucagon and, concomitantly, using glucagon to treat and prevent hypoglycemia." (PMID 37715091, 2024). "The failure of insulin-induced hypoglycaemia to increase plasma glucagon in T1D was first documented 50 years ago2." (PMID 39313541, 2024). "The dysfunction of pancreatic α cells is manifests with the insufficient response of glucagon to hypoglycemia and its incomplete suppression after oral glucose administration, which is similar to that of patients with type 2 DM." (PMID 39596226, 2024). "Mini-dose glucagon can be an important tool for treating and preventing mild to moderate hypoglycemia in individuals with T1D." (PMID 39944479, 2024). "An episode of severe hypoglycemia-induced unconsciousness necessitated intramuscular glucagon administration, resulting in regained consciousness." (PMID 39677258, 2024). "These processes disrupt the normal response to hypoglycemia, leading to a blunted release of counterregulatory hormones such as glucagon, epinephrine, and growth hormone." (PMID 38397994, 2024). "Impaired counterregulatory responses are thought to contribute, including a reduction in glucagon response to hypoglycemia, similar to what has been demonstrated in mixed meal tests in patients following TPIAT." (PMID 39450137, 2024). "A glucagon response to hypoglycemia was observed in HFF control animals, but the response was largely absent in the T2D controls." (PMID 38510652, 2024). "On the other hand, exogenous glucagon can be a useful addition in dual hormone pump systems, aiming to prevent hypoglycemia, especially in the case of exercise-induced hypoglycemia during aerobic exercise when compared to single hormone pump systems." (PMID 39766270, 2024). "In hypoglycemia, glucagon increases the blood glucose level by glycogenolysis and gluconeogenesis and inhibits glycogenesis in the liver." (PMID 39594592, 2024). "For instance, glucagon release is stimulated by hypoglycemia, starvation, exercise, and protein-rich meals, and insulin release is stimulated by a hyperglycemic condition." (PMID 38921471, 2024). "Clinically, glucagon injections are primarily used to treat hypoglycemia, cardiogenic shock, and other adverse reactions, including nausea, vomiting, hyperglycemia, and hypokalemia." (PMID 38072640, 2024). "SSTR2 antagonists increased the glucagon response and reduced incidence of hypoglycemia, which was more pronounced with ZT-01 than PRL-2903." (PMID 38510652, 2024).
Hypoglycemia (continued). "In opposing studies, episodes of fatal hypoglycaemia were reported, which probably go to the poor ability of alpha cells to produce glucagon to act as a counterbalance." (PMID 39424751, 2024). "High-fat-diet fed and low-dose streptozocin-treated C57BL/6N mice were exposed to one (acute hypoglycaemia [AH]) or multiple (recurrent hypoglycaemia [RH]) insulin-induced hypoglycaemic episodes and plasma glucagon levels were measured." (PMID 38017352, 2024). "Severe hypoglycemia occurring at home or school should be treated immediately with subcutaneous or intranasal glucagon." (PMID 38894740, 2024). "Individuals with ongoing hypoglycemia should also have access to glucagon therapy for emergency rescue." (PMID 37454648, 2024). "Due to its ability to rapidly reverse hypoglycemia, significant effort has been expended to develop stable glucagon formulations to treat hypoglycemia as well as a partner to insulin in bihormonal pump therapy." (PMID 38477666, 2024). "Despite these findings, over a century after its discovery, glucagon’s clinical use has primarily remained as an emergency treatment for severe hypoglycemia." (PMID 38477666, 2024). "Although insulin and glucagon are also able to act as counter-regulatory hormones following hypoglycemia, it is mostly the adrenaline-driven mechanisms that restore normal glucose levels during hypoglycemic events in patients with diabetes." (PMID 39375537, 2024). "Adding glucagon to the treatment algorithm allows for more aggressive insulin treatment, as glucagon is used to counteract insulin-induced hypoglycemia or predicted hypoglycemia in the near future." (PMID 37715091, 2024). "Studies on murine SOD1G93A ALS models revealed elevated glucagon levels following fasting or insulin-induced hypoglycemia despite minimal changes in overall blood glucose levels." (PMID 38791099, 2024). "It is believed that the purpose of the glucagon release is, by stimulating hepatic glucose production, to avert hypoglycemia resulting from the concomitant insulin secretion." (PMID 39275186, 2024). "Conventional treatments for sulfonylurea-induced hypoglycemia involve glucagon and intravenous and oral dextrose combined." (PMID 39347364, 2024). "Simultaneously, insulin and glucagon blood concentrations in dogs with hypoglycemia preoperatively and postoperatively were compared to verify the physiological responses to hypoglycemia." (PMID 38393097, 2024). "It stimulates insulin secretion during euglycemia and hypoglycemia, and it stimulates glucagon secretion besides, glucose-dependent insulinotropic polypeptide increases tri-acyl glycerol (uptake in adipose tissue and decreases bone resorption." (PMID 39493778, 2024). "Although intuition studies regarding nasal use are rare, a study reported the following: to evaluate the ease of use, user preference, and effort required, nasal glucagon was compared with injectable glucagon in a simulation of severe hypoglycemia." (PMID 38392943, 2024). "This was supported by inappropriately low ketones and free fatty acids at the time of hypoglycemia as well as a positive response to glucagon stimulation with a blood glucose rise of 60 mg/dL (3.3 mmol/L) within 30 minutes." (PMID 39659385, 2024). "The effectiveness of somatostatin analogues in preventing hypoglycemic episodes is estimated at 40–60% of cases, but it can inhibit the release of counterregulatory hormones, such as glucagon, which can even worsen hypoglycemia in some patients." (PMID 39057179, 2024). "The counterregulatory response of the key hormones epinephrine, GH, and glucagon was dampened after recurrent hypoglycemia when participants slept regularly compared to sleep deprivation." (PMID 38397994, 2024). "After another instance of hypoglycemia, he underwent a glucagon challenge and received 1 mg of glucagon; he had an increase in his blood glucose of 60 mg/dL (3.3 mmol/L) in a period of 28 minutes, which was deemed a positive response." (PMID 39659385, 2024).
Hypoglycemia (continued). "It has been confirmed that the neurohumoral regulatory response induced by hypoglycemia included the termination of the release of endogenous insulin, the release of glucagon, and the activation of the pituitary-adrenal axis." (PMID 37051050, 2023). "Considering the crucial role of glucagon in regulating fasting blood glucose level under fasting or hypoglycemia condition, melatonin improved insulin sensitivity should be limited to the fasting state, requiring, further investigation." (PMID 37051358, 2023). "At 5 years old, on weaning of steroids, hypoglycaemia recurred, requiring 10% intravenous glucose, subcutaneous glucagon infusion, and continuous percutaneous feeding including 12 h of overnight feeding and 3-hourly starch-enriched boluses during the day." (PMID 37974153, 2023). "The transient neonatal hypoglycemia is accompanied by the secretion of glucagon, which turns on the glycogenolysis program by PYGL phosphorylation and GDE induction." (PMID 37826876, 2023). "In a prototypical fashion, glucagon is released upon hypoglycemia to elevate glucose by acting on the liver while elevated glucose induces the secretion of insulin which leads to sugar uptake by peripheral tissues." (PMID 37645413, 2023). "By releasing glucagon into the bloodstream, the system would enable corrections of hypoglycemia by mobilizing hepatic glycogen, which is released into the bloodstream in the form of glucose, promoting reversal of the hypoglycemic condition." (PMID 36748934, 2023). "Previous work has demonstrated that the ingestion of a mixed meal prior to insulin-induced hypoglycemia also increases glucagon secretion, most likely due to hyperaminoacidemia." (PMID 37166980, 2023). "In healthy people without diabetes, endogenous insulin secretion is closed off, and counterregulatory hormones (glucagon, epinephrine, and norepinephrine) are released in response to hypoglycemia." (PMID 36769430, 2023). "When challenged with exogenous glucagon, a larger amount of glycogen would consequently be available for glycogenolysis, compared with the group in which hypoglycaemia was induced using HI." (PMID 36404376, 2023). "Previously, using glucose clamp techniques, our research group has demonstrated that overweight and insulin resistant individuals have augmented responses of the cortisol axis to hypoglycemia and impaired suppression of glucagon during hyperglycemia." (PMID 37400734, 2023). "It is worth noting that glucagon is the counterregulatory hormone to insulin, induced by fasting or hypoglycemia to raise blood glucose through action mediated in the liver." (PMID 37051358, 2023). "Instead, the endogenous secretion of insulin and glucagon was inhibited with somatostatin immediately prior to hypoglycemia and both hormones were matched between groups using intraportal infusions." (PMID 37166980, 2023). "For glucagon, we also examined the PD profile, that is, the profile of blood glucose levels, in hypoglycemia‐induced animals." (PMID 37206225, 2023). "In mice carrying a targeted disruption of the CREB gene or expressing a dominant negative CREB protein in the liver, the induction of pgc-1α, g6pc, and pck1 by glucagon was blocked, and this led to severe hypoglycemia." (PMID 37048171, 2023). "In general, prandial insulin is injected two or three times daily before each meal, and glucagon injection is used to treat severe hypoglycemia." (PMID 36684080, 2023). "A previous study found that inhibition of UCP-2 by genipin reduced hypoglycemia-induced glucagon secretion from pancreatic α-cells, thereby slowing the rate of blood glucose recovery during an insulin tolerance test." (PMID 36768454, 2023). "In humans, Adamson and colleagues reported that a 72-hour fast lowered glucagon and epinephrine responses to hypoglycemia, and also lowered the need for exogenous glucose, which is not incompatible with our data." (PMID 37166980, 2023).